EIF5A (eukaryotic translation initiation factor 5A)
Diseases named in the same sentence as EIF5A in open-access papers (continued):
Sharing a sentence is not in itself a finding about the gene and the disease.
pituitary adenomas (1 paper, 2022). "Compared with aggressive pituitary adenomas, PTBP1 and eIF5A were highly expressed in primary pituitary adenomas." (PMID 35836612, 2022). "In pituitary adenomas, the subsequent immunohistochemical results confirmed the differential expression of SLC27A1, PTBP1, and EIF5A genes in aggressive pituitary adenomas and primary pituitary adenomas, and the difference was statistically significant." (PMID 35836612, 2022). "In summary, our study demonstrates that the high expression of SLC27A1 and the low expressions of PTBP1 and EIF5A predict the progression of an aggressive pituitary adenoma." (PMID 35836612, 2022). "After the data of the two groups were overlapped, it was found that PTBP1 and EIF5A were highly expressed in the primary pituitary adenomas and normal control pituitary tumor cells, and SLC27A1 was highly expressed in aggressive pituitary adenomas and TMZ-treated ATt20 cells." (PMID 35836612, 2022). "Therefore, SLC27A1, PTBP1, and EIF5A may be important molecular markers for predicting the recurrence of pituitary adenomas." (PMID 35836612, 2022). "In tumour tissues, mRNA sequencing showed that PTBP1 and EIF5A were significantly overexpressed in primary pituitary adenomas and SLC27A1 was significantly overexpressed in aggressive pituitary adenomas." (PMID 35836612, 2022). "High expression of SLC27A1 and low expression of EIF5A and PTBP1 may be potential indicators to predict the progression of aggressive pituitary adenomas, and patients with high SLC27A1 subtype may be sensitive to TMZ in clinical treatments." (PMID 35836612, 2022). "Through a comprehensive analysis of the results of histological and cytological experiments, we found that the expression of SLC27A1 was significantly high in aggressive pituitary adenomas and TMZ therapy sensitive cell lines, while the expression of PTBP1 and EIF5A was significantly decreased." (PMID 35836612, 2022).
psoriasis (1 paper, 2025). An autoimmune condition characterized by red, well-delineated plaques with silvery scales that are usually on the extensor surfaces and scalp. "Here, we demonstrate that in psoriasis, HKGs such as STAT3, PPIF, and EIF5A are co‐opted by the IL‐17/IL‐6 signaling axis to drive keratinocyte activation." (PMID 40959079, 2025).
Seizure (1 paper, 2024). A seizure is an intermittent abnormality of nervous system physiology characterized by a transient occurrence of signs and/or symptoms due to abnormal excessive or synchronous neuronal activity in the brain. "Seizures were not reported in patients with loss-of-function EIF5A mutations, nor in an eIF5A-deficient zebrafish model." (PMID 39334388, 2024).
vitiligo (1 paper, 2024). Generalized well circumscribed patches of leukoderma that are generally distributed over symmetric body locations and is due to autoimmune destruction of melanocytes. "Cluster12 keratinocyte RBP-expression groups, namely, ZC3H12A, S100A9, CYCS, and EIF5A, were also enriched in the apoptotic pathway in the patients with vitiligo." (PMID 38438962, 2024).
cancer (82 papers, 2012 to 2025). A tumor composed of atypical neoplastic, often pleomorphic cells that invade other tissues. "Elevated levels of polyamines, ODC, and eIF5A proteins are often observed in various cancer types and are associated with their hyperproliferative phenotypes." (PMID 40617352, 2025). "Although dysregulation of EIF5A has been associated with cancer development as well as inflammation diseases, the role of EIF5A in IBD remains to be elucidated." (PMID 40621466, 2025). "We further quantified that 12% of cancer‐linked genes were T‐cell enriched, among which EIF5A and PSMB5 are targets of anticancer drugs under clinical trial investigation." (PMID 41216857, 2025). "eIF5A has been implicated in cancer progression, chemo-resistance, and metastasis, underscoring its significance in tumor biology." (PMID 39198484, 2024). "Like eIF5A, Hsp27 is associated with cell proliferation and is highly expressed in many human cancers where it enhances cell survival via activation of NF-κB." (PMID 36838674, 2023). "Overexpression of eIF5A has been linked with the development of a variety of cancers and inhibitors of the molecule have been proposed for anti-cancer clinical applications." (PMID 36511302, 2022). "eIF5A and its hypusine modification have been implicated in various human pathological conditions including cancer, diabetes, inflammation, and retroviral infections." (PMID 34273022, 2022). "The relationship between eIF5A and apoptosis has been reported in cancer cell lines, however the mechanisms underlying this link remains somehow controversial." (PMID 34952646, 2021). "eIF5A-1 has been implicated in diabetes, several cancer types, viral infections and neurological diseases." (PMID 33379337, 2020). "Both eIF5A isoforms have been linked to cancer functions, though, given the weak or undetectable expression of eIF5A2 in most tissues, their overexpression in various cancers is more readily identified." (PMID 29799508, 2018). "eIF5B, eIF5, and eIF5A all contain links into hallmark stages and mechanisms of cancer proliferation, and manipulation of these proteins offers a potential regulation point of gene expression regulation." (PMID 28083147, 2016). "Interestingly, the activity changes in EIF5A were linked to cancer development, particularly its higher expression in GBM patient samples compared with normal glia cells." (PMID 37835380, 2023). "Polyamine-EIF5A axis could have a broader role in general mucosal dysfunction as well as cancer predisposition in HIV+ patients, but this study focused only on its role in Th dysfunction." (PMID 36693889, 2023). "eIF5A, especially in cancer, has been linked to the regulation of various signalling molecules." (PMID 36511302, 2022). "Since acetylation and nuclear localisation of eIF5A is tightly linked to its inactivation, lysine deacetylase inhibitors may be an interesting therapeutic approach for cancer." (PMID 36511302, 2022). "eIF5A has been associated with development and progression of multiple types of cancer." (PMID 32298235, 2020). "The association between eIF5A inhibition and mitochondrial dysfunction, either as a primary or secondary effect, suggests the elongation factor could be a putative target for mitochondrial-dependent cancer therapeutic strategies." (PMID 41390489, 2025). "One eIF5A isoform in humans is abundantly expressed in most cells, essential for cell proliferation, while the other isoform is undetectable or only weakly expressed in most cells and tissues, but highly expressed in various cancerous cells, and thus suggested to be associated with cancers." (PMID 33592076, 2021). "To determine the utility of targeting eIF5A as an anti-cancer therapeutic we analysed the temporal changes in mRNA translation following treatment with GC7." (PMID 41390489, 2025). "Its inhibition slows the growth of cancer cells and reduces metastasis, and blockade of eIF5A hypusination limits colorectal cancer in mice." (PMID 39937781, 2025).
cancer (continued). "Recently, a study showed that eIF5A regulates the selection of MYC-mRNA start codon in cancer cells." (PMID 39779613, 2025). "In this study we explored the impact of eIF5A inhibition on overall translation and its potential ramifications for cancer cell growth." (PMID 41390489, 2025). "Our findings suggest that cancer cells with high OXPHOS levels or a reliance on mitochondria for energy production would exhibit increased sensitivity to eIF5A inhibition." (PMID 41390489, 2025). "Mechanistically, EIF5A promoted cancer stem cell (CSC) characteristics through the Hedgehog signaling pathway." (PMID 39290702, 2024). "An amino acid such as Orn acts as a substrate for polyamines, which promote the growth of cancer cells due to the activation of eukaryotic translation initiation factor 5A (EIF5A), which initiates protein translation." (PMID 39456554, 2024). "Facilitating resistance of cancer cells to the stress conditions to which they are usually subjected is among the multiple proposed functions of eIF5A." (PMID 38229033, 2024). "EIF5A’s importance in cancer progression has garnered attention, but its full significance remains to be uncovered." (PMID 39290702, 2024). "In the context of cancer, eIF5A hypusination facilitates translation elongation of MYC and regulates the focal adhesion kinase PEAK1, both of which contribute to tumor growth." (PMID 38689086, 2024). "eIF5A proteins are important in physiological and pathophysiological processes including protein synthesis and biomass production in cancer, embryonic and neuronal development, Alzheimer's disease, and viral replication (Ebola, Zika, Dengue, other)." (PMID 36848144, 2023). "Similar observations with therapeutic potential have been made for hypusinated eIF5A in different cancer types." (PMID 36838674, 2023). "eIF5A plays a vital role in inflammation, such as macrophage activation, B cell immunity, and cancer progression." (PMID 36826549, 2023). "There is a clear connection between eIF5A levels and activity in cancer suggesting that eIF5A and the hypusination pathways are good targets for anti-cancer drug development." (PMID 36511302, 2022). "The eIF5A cancer stroma expression levels showed that OC with low levels of eIF5A cancer stroma expression had an OS of 45.4 months (CI95 38.9–52.0 months) and 36.5 months (CI95 22.7–50.4 months) in high levels of expression in eIF5A cancer stroma expression." (PMID 35718769, 2022). "Previous studies have established that an overexpression of eIF5A was connected to worse overall outcomes in different cancer subtypes." (PMID 35718769, 2022). "GC7 inhibits eIF5A hypusination via a block of DHPS resulting in cell growth stall in various cancers." (PMID 36511302, 2022). "It is important to understand how eIF5A can help to alleviate elongation stalls under stress conditions for cancer treatments as often tumour cells grow under stressful environments." (PMID 36511302, 2022). "Although the mechanism(s) via which eIF5A functions in cancer development is unclear, recent data have revealed a pleiotropic mode of action for the protein in different types of tissues and organisms." (PMID 36511302, 2022). "EIF5A and its hypusination have been identified as relevant factors in cancer and its treatment, as well as in aging." (PMID 36361762, 2022). "Knowledge of the details of these complex regulatory mechanisms can help to understand why combinatorial therapies, which employ DFMO to inhibit ODC, and GC7 to inhibit eIF5A hypusination, are particularly effective in the treatments of certain cancers." (PMID 36361762, 2022).
cancer (continued). "Mean survival in low eIF5A cancer stroma expression was 41.1 months (CI95 34.2–48.0 months) and 27.4 months (CI95 13.9–41.0 months) in eIF5A cancer stroma high expression." (PMID 35718769, 2022). "Primary factor analysis showed a statistically significant difference in RFS for the subunit eIF5A in nuclear factor expression and in cancer stroma expression." (PMID 35718769, 2022). "A correlation between expression of eIF5A and cancer has been established and both eIF5A1 and eIF5A2 have been proposed to act as oncogenes." (PMID 36511302, 2022). "After adjusting for within group differences between serous and mucinous BLTs, eIF5A was significantly overexpressed in the cancer stroma and cytoplasm of BL." (PMID 35718769, 2022). "Eukaryotic translation initiation factor 5A2 (eIF5A2), an isoform of eIF5A, plays an essential role in mRNA translation, and is an oncogene that regulates cell proliferation, invasion, metastasis, and cancer progression in several cancers." (PMID 34864817, 2021). "From a clinical point of view, the pharmacological targeting of eIF5A was initially considered to be a means to inhibit cell proliferation and thus as a potential treatment for cancer." (PMID 34952646, 2021). "Over-expression of eIF-5A has often shown a strong correlation with cancer and has been considered as a candidate oncogene." (PMID 34039408, 2021). "In humans, two eIF5A isoforms are known to exert specialized activities in certain tissues and cancer cells in addition to basic overlapping functions." (PMID 33592076, 2021). "Expression of the eIF5A gene has been examined in several cancers and cancer cell lines, both at the protein and RNA levels demonstrating unambiguously its over-expression in transformed cells." (PMID 32605139, 2020). "The first isoform (eIF5A-1) is constitutively expressed in mammalian cells and overexpressed in human cancer tissues." (PMID 32235505, 2020). "Emerging data are showing that hypusinated EIF5A regulates key cellular processes such as autophagy, senescence, polyamine homeostasis, energy metabolism, and plays a role in cancer." (PMID 33303756, 2020). "In contrast to eIF5A, the expression of the other isoform (eIF5A-2) was detected only in specific tissues (testis and brain) or in various cancer types including colon, ovarian, bladder and liver." (PMID 32235505, 2020). "The most studied translation factors that function as oncogenes during tumor formation, growth, invasion and metastasis in various cancers include eIF4E and its repressors 4E-BPs, as well as eIF2α, eIF3, eIF2α, eIF5A." (PMID 32973493, 2020). "Expanding these observations in vivo using mouse xenograft assays, eIF5A silencing in cancer cells pretreated with HA led to a significant increase in tumor growth." (PMID 33188200, 2020). "Hypusinated eIF5A is essential for tumour growth, and its level of expression is closely related to the aggressiveness of cancers." (PMID 32235505, 2020). "KRas in turn promotes EIF5A protein expression, thus generating a positive feed forward loop that promotes glutamine-dependent cancer cell growth." (PMID 33303756, 2020). "EIF5A2, a second isoform of EIF5A, has been observed to be up-regulated in many type tumors and is an important carcinogenic biomarker in many cancers." (PMID 33308276, 2020). "Enhanced eIF5A2 expression correlates with poor prognosis and poor response for chemotherapeutic drugs in patients with cancers, suggesting that eIF5A is a useful biomarker in the prediction of cancer prognosis and drug response." (PMID 33200656, 2020). "Recent studies have shown that EIF5A is overexpressed in various cancers, including CRC, where it correlates with poor prognosis." (PMID 33303756, 2020). "It has previously been shown that eIF5A and the DHS-mediated hypusine modification are linked to cancer." (PMID 24832488, 2014).
cancer (continued). "In this regard, our data support the assumption that the final step of hypusine modification of eIF5A is a crucial regulator of different characteristics of cancer cells." (PMID 24832488, 2014). "It is suggested that up-regulation of eIF5A expression contributes to proliferation of cancer cells most likely by constitutive activation of the protein synthesis pathway." (PMID 23029619, 2012). "Eukaryotic translation initiation factor 5A (eIF5A) is one of the eIFs involved in translation initiation and eIF5A2, one of its isoforms, is upregulated in various cancers including HCC as a result of chromosomal instability, where it resides." (PMID 23029619, 2012). "Early research on the function of eIF5A as a translational regulator in cancer suggests that it may be a promising therapeutic target." (PMID 39779613, 2025). "The biological role and significance of EIF5A lies in its pivotal regulation of essential cellular processes like protein synthesis, tumor proliferation, and apoptosis, which are crucial for cancer development." (PMID 39290702, 2024). "The eukaryotic translation initiation protein eIF5A is a highly conserved and essential factor that plays a critical role in different physiological and pathological processes including stress response and cancer." (PMID 38229033, 2024). "The regulation of SGs formation and function by eIF5A has been suggested as a mechanism that may contribute to the protection of cancer cells from cellular stress." (PMID 38229033, 2024). "Based on our finding of a substantial decrease in tumor growth in vivo following a decrease in eIF5A hypusination in TAMs, targeting eIF5A could be a promising cancer treatment in the clinical setting." (PMID 38689086, 2024). "The polyamine-eIF5A-hypusine axis is emerging as a potential therapeutic opportunity in cancer." (PMID 39198484, 2024). "In addition, some nuclear transport receptors also function as chaperones for proteins implicated in cancers such as PTEN and eIF5A." (PMID 39353922, 2024). "Further exploration of the intricate interplay between eIF5A, polyamines, and mitochondrial function may offer promising avenues for therapeutic interventions in the field of aging and cancer research." (PMID 39198484, 2024). "eIF5A is involved in protein synthesis, cancer progression, and chemo-resistance." (PMID 39198484, 2024). "The metal chelating compounds could efficiently suppress deoxyhypusine hydroxylation in eIF5A, and arrest the progression of cell cycle in mammalian cells, including human cancer cells and HUVEC cells, at the boundary of G1/S." (PMID 37957566, 2023). "We next addressed whether high eIF-5A levels were associated with bad prognosis in LUAD and found that cancer patients with high EIF5A2 levels showed poorer prognosis than the rest of patients." (PMID 36915194, 2023). "Previous studies have found that eIF5A can regulate cancer stem cells (CSCs)." (PMID 35725615, 2022). "The downregulation of eIF5A increased the production of ROS by inducing mitochondrial damage, which may be an important factor in inducing cancer ferroptosis." (PMID 35874632, 2022). "Taken together eIF5A could be a regulator of SGs formation and function and through this protect cancer cells from cellular stress." (PMID 36511302, 2022). "Notably, eIF5A depletion during HA significantly increased the sensitivity of cancer cells to conventional antiproliferative drugs, e.g., vincristine and temozolomide." (PMID 33188200, 2020). "The efficacy of cancer treatments could potentially be improved by targeting eIF5A alongside routine chemotherapies." (PMID 33188200, 2020). "eIF5A is constitutively expressed in mammalian cells and is essential for normal mammalian development and is abundant in proliferating cells such as in human cancer tissues." (PMID 32605139, 2020). "Taken together, these data suggest that eIF5A could be a promising new target for the development of drugs targeting specific subtypes of cancer." (PMID 32298235, 2020).